LY6E (lymphocyte antigen 6 family member E)
Description:
GPI-anchored cell surface protein that regulates T-lymphocytes proliferation, differentiation, and activation. Regulates the T-cell receptor (TCR) signaling by interacting with component CD3Z/CD247 at the plasma membrane, leading to CD3Z/CD247 phosphorylation modulation (By similarity). Restricts the entry of human coronaviruses, including SARS-CoV, MERS-CoV and SARS-CoV-2, by interfering with spike protein-mediated membrane fusion. Also plays an essential role in placenta formation by acting as the main receptor for syncytin-A (SynA). Therefore, participates in the normal fusion of syncytiotrophoblast layer I (SynT-I) and in the proper morphogenesis of both fetal and maternal vasculatures within the placenta. May also act as a modulator of nicotinic acetylcholine receptors (nAChRs) activity (By similarity). (Microbial infection) Promotes entry, likely through an enhanced virus-cell fusion process, of various viruses including HIV-1, West Nile virus, dengue virus and Zika virus. In contrast, the paramyxovirus PIV5, which enters at the plasma membrane, does not require LY6E. Mechanistically, adopts a microtubule-like organization upon viral infection and enhances viral uncoating after endosomal escape.
Synonyms: RIG-E; SCA-2; TSA-1; RIGE; SCA2
Tractability: Antibody: its Gene Ontology location is reachable by antibodies, with high confidence; UniProt places it where antibodies can reach, with medium confidence; UniProt predicts a signal peptide or a membrane-spanning region. Other modalities: a drug acting on it is in phase 1 trials.
Gene: Protein-coding gene on chromosome 8 (143,012,722 to 143,023,832, forward strand). Ensembl gene ENSG00000160932.
Subcellular location: Cell membrane
Pathways (Reactome):
Disease: Dengue Virus Attachment and Entry
Metabolism of proteins: Post-translational modification: synthesis of GPI-anchored proteins
Gene Ontology:
Molecular function: protein binding; acetylcholine receptor binding; acetylcholine receptor inhibitor activity
Biological process: host-mediated suppression of symbiont invasion; acetylcholine receptor signaling pathway; cell surface receptor signaling pathway
Cellular component: extracellular region; plasma membrane; synapse
Genetic constraint (gnomAD): Loss-of-function variants: 4 observed, 8.04 expected, observed/expected ratio (o/e) 0.5, 90% interval 0.24 to 1.14. That is too few expected variants to judge how well the gene tolerates losing a copy. Missense variants: 156 observed, 173.86 expected, observed/expected ratio (o/e) 0.9, 90% interval 0.79 to 1.02. Synonymous variants: 81 observed, 82.05 expected, observed/expected ratio (o/e) 0.99, 90% interval 0.82 to 1.19.
Homologues: Orthologues: pig LY6E (77% identical), dog LY6E (73% identical), guinea pig LY6E (68% identical), rat Ly6e (63% identical), mouse Ly6e (61% identical). Paralogues in human: GPIHBP1 (31% identical), PSCA (29% identical).
Diseases named in the same sentence as LY6E in open-access papers:
LY6E is named in the same sentence as 69 diseases in open-access papers, as found by Europe PMC text mining. Sharing a sentence is not in itself a finding about the gene and the disease. The quoted sentences say what the papers report.
viral infection (22 papers, 2013 to 2025). "Aside from the identified primary functions, namely, the regulation of T cell activation, proliferation, development, tumor metastasis, and differentiation, LY6E is associated with viral infections." (PMID 38169284, 2024). "LY6E encodes an interferon-inducible protein, which has been shown to regulate viral infection in a cell type-dependent manner." (PMID 37007947, 2023). "The interferon-induced gene LY6E increases virus infection, but the underlying mechanism is poorly understood." (PMID 30190477, 2018). "Six genes were closely associated with viral infection, namely, LY6E, receptor-type tyrosine-protein phosphatase S (PTPRS), neurogenic locus notch homolog protein 3 (NOTCH3), tripartite motif containing 56 (TRIM56), ring finger protein 135 (RNF135), and growth arrest-specific 6 (GAS6)." (PMID 38169284, 2024). "Consequently, viral infection and associated pathogenesis have been associated with altered LY6E gene expression." (PMID 31684192, 2019). "The ISG LY6E has previously been implicated by us and others to modulate viral infection." (PMID 30190477, 2018). "LY6E may be one member of a growing class of ISGs that increases cellular susceptibility to viral infection, but whether the phenotypes in this class are all a result of viral hijacking remains unclear." (PMID 30190477, 2018). "In this respect, it is also reported that types I and III IFNs are important cytokines to inhibit viral infection by inducing antiviral genes including anti-SARS-CoV-2 genes such as LY6E and BST2." (PMID 36703213, 2023). "The LY6E protein not only plays an important role in immune regulation but also participates in the viral infection process of coronavirus, including SARS-CoV, MERS-CoV, and SARS-CoV-2." (PMID 35928229, 2022). "Altogether, the actions of LY6E on virus infection seem to be tricky, and therefore, further investigation will be needed to fully elucidate the pro- or anti-viral roles of LY6E in virus infections and replications." (PMID 35468127, 2022). "LY6E plays an important role in immune regulation and participates in the viral infection process of coronavirus." (PMID 35928229, 2022). "Nevertheless, the exact mechanisms through which Ly6E modulates viral infection virus-wise, and sometimes even cell type-dependently, require further characterization." (PMID 32708319, 2020). "This enhancing effect of Ly6E on viral infection has also been observed in other enveloped RNA viruses such as in West Nile virus (WNV), dengue virus (DEN), Zika virus (ZIKV), O’nyong nyong virus (ONNV) and Chikungunya virus (CHIKV) among others." (PMID 32708319, 2020). "This is the case of gene Ly6E, which has been shown to play an important role in viral infection, as well as various orthologs of the same gene." (PMID 32708319, 2020). "Further understanding of the role and mechanism of LY6E in viral infections will establish a scientific basis for development of therapeutics to harness its function for the treatment of viral diseases." (PMID 32641482, 2020). "Third, LY6E can regulate cell signaling, including the host immune response, which is essential for defending against viral infections." (PMID 31684192, 2019). "LY6E has been previously shown to promote viral infection and it is essential for clathrin-mediated endocytosis of virus particles, a pathway that is also used by FMDV." (PMID 30642035, 2019). "Because TGFβ is widely implicated in viral infection and pathogenesis, it would be important to explore the possible involvement of LY6E in TGFβ-regulated viral infections." (PMID 31684192, 2019). "In this review, we summarize the current knowledge of LY6E in the context of viral infection, particularly viral entry." (PMID 31684192, 2019). "A critical question is how LY6E modulates viral infection, and often in a cell type-dependent and virus-specific manner." (PMID 31684192, 2019).
viral infection (continued). "In screens to identify ISGs that modulate viral infection, we previously showed that ectopic expression of human LY6E by lentiviral transduction enhanced the infectivity of multiple, genetically diverse viruses." (PMID 30190477, 2018). "In the data presented here, we demonstrate that LY6E enhances viral infection in a cell type- and virus-specific manner." (PMID 30190477, 2018). "LY6E is the first member of the LY6/uPAR protein family that has been validated in several studies to enhance viral infection." (PMID 30190477, 2018). "The antiviral-ISG, including GBP1, IFI44, IFIH1, IFIT1, MX1, and LY6E, were the most common group of up-regulated genes after influenza infection, yellow fever vaccination, and during febrile episodes of dengue hemorrhagic fever." (PMID 24069471, 2013). "IFNs inhibit viral infection by inducing several genes, including LY6E." (PMID 38169284, 2024). "It is reported that LY6E could control CoV infection and pathogenesis and confer immune control of viral diseases, including SARS-CoV-2." (PMID 35450295, 2022). "We observed that adult patients with epileptic seizures had peripheral whole blood that included miR-654-3p, miR-323a-3p, miR-323b, miR-3283p, miR-342-5p, miR-150-5p, miR-3395p and IFIT3, IFIT1, IFI44L, OAS3, and LY6E in the pathways connected to viral infection." (PMID 36172025, 2022). "In summary, while it is very interesting to know that LY6E is capable of modulating the entry of many RNA viruses, we have only begun to uncover the mechanisms of this fascinating host factor and define its pathobiological role in virus infection." (PMID 32641482, 2020). "Moreover, the results of the DEG analyses indicate that the sole knockout of gene Ly6E in HSC considerably affects the upregulating genetic program normally triggered by viral infection in wild type individuals (in both liver and spleen)." (PMID 32708319, 2020). "Emerging evidence indicates that LY6E is also involved in the modulation of viral infection." (PMID 31684192, 2019). "Because LY6E is ubiquitously expressed in multiple human tissues, we next sought to test whether ectopic LY6E expression enhanced viral infection in different cellular backgrounds." (PMID 30190477, 2018). "To assess whether LY6E could enhance viral infection via transcriptome modulation, we used RNA-Seq to compare gene expression profiles of STAT1-/- fibroblasts expressing an empty vector as a control versus cells expressing LY6E." (PMID 30190477, 2018). "The function of LY6E in the glycosylphosphatidylinositol (GPI) anchor of cell membrane proteins is of great importance in cell signal transduction, immune regulation, virus infection, tumor metastasis and cellular adhesion." (PMID 40180998, 2025). "ITGAM, RUNX1, and PSTPIP2 formed one cluster with high expression in subjects with confirmed bacterial infections, whereas LY6E and IRF-9 formed another cluster with high expression, mainly in patients with confirmed viral infections." (PMID 36900096, 2023). "ITGAM, RUNX1, and PSTPIP2 formed one cluster with high expression in subjects with confirmed bacterial infections, whereas LY6E and IRF-9 formed another cluster with high expression in patients with confirmed viral infections." (PMID 36900096, 2023). "In a screen to identify antiviral ISGs, we unexpectedly found that LY6E, a member of the LY6/uPAR family, enhanced viral infection." (PMID 30190477, 2018). "LY6E downregulates CD14, a key molecule in the TLR4/CD14/NF-κB pathway, inducing a negative feedback loop for innate immune activation and providing a new pathway for viral infection." (PMID 38169284, 2024). "Notably, expression of cellular factors at levels insufficient for protein detection can nevertheless affect virus infection, as demonstrated for the alphavirus receptor, MXRA8, and the interferon stimulated gene, LY6E." (PMID 38712102, 2024).
viral infection (continued). "However, for HCoV-OC43, overexpression of Ly6E was shown to inhibit virus entry and infection in HEK293 and A549 cells, whereas knockdown of Ly6E enhanced viral infection in HepG2 cells." (PMID 34058196, 2021). "Linking LY6E to viral infection did not occur until the early 2000s, and recently there has been increasing interest in the study for the role of LY6E in viral interactions." (PMID 31684192, 2019). "Similar results were obtained, confirming that endogenous LY6E is not essential for viral infection, but is required for optimal viral infectivity." (PMID 30190477, 2018). "Indeed, a recently reported set of studies highlighted the ISG Ly6E as a factor that promotes, rather than inhibits, viral infection, and the SARS-CoV-2 entry factor ACE2 is also induced by the actions of IFNs." (PMID 33849978, 2021). "Besides, LY6E and MCOLN2 directly enhance viral infection rather than inhibit IFN signaling." (PMID 40245000, 2025).
breast carcinoma (14 papers, 2013 to 2025). "LY6E overexpression has been associated with drug resistance in several cancers, such as breast cancer, gastric cancer, and lung cancer." (PMID 39408764, 2024). "LY6E expression levels were significantly higher in human breast cancers than in normal breast tissues, and were strongly associated with the poor prognoses of various cancer patients." (PMID 27589564, 2016). "High expression levels of LY6E have been reported in basal-like breast cancer cell lines and have been associated with pulmonary breast cancer metastasis." (PMID 27589564, 2016). "LY6E expression levels were significantly higher in basal-like subtype human breast cancers than in normal breast tissues, and were strongly associated with the poor prognoses of various types of cancer patients." (PMID 27589564, 2016). "A survey of more than 130 published clinical studies found that increased expression of LY6E is associated with poor survival outcome in multiple malignancies and it has also been found to be important for drug resistance and tumor immune escape in breast cancer." (PMID 33837451, 2021). "To understand a possible association between Sca-1 and TME, we performed differential expression analysis between two cohorts of breast cancer samples (TCGA) with high or low levels of LY6E." (PMID 40634316, 2025). "Regulation of the TGF-β pathway with Ly6 proteins in human cells has been shown for Ly6E/K in breast cancer cells." (PMID 38356711, 2024). "Overexpression of Ly6E promoted cancer cell growth and metastasis in gastric cancer, drug resistance and immune escape in breast cancer, and TGF-β-induced PD-L1 activation and binding of NK cells to cancer cells." (PMID 35865015, 2022). "On the other hand, GATA3, the low expression of which has been linked to the malignant progression of breast cancers, has been shown to negatively regulate LY6E expression in breast cancer cells." (PMID 27589564, 2016). "The expression levels of LY6E were significantly higher in basal-like breast cancer than in surrounding normal breast tissues in the TCGA data analysis." (PMID 27589564, 2016). "The microarray and RNA-seq data sets from 2012 TCGA showed significantly higher expression levels of LY6E in basal-like breast cancer than in surrounding normal breast tissues." (PMID 27589564, 2016). "We have tested for human Ly6E and Ly6K in breast cancer and delineated the molecular mechanism behind cancer cell growth, metastasis and drug resistance (being published separately)." (PMID 26862846, 2016). "Ly6E mRNA expression was significantly increased in breast cancer (n=2613) than normal tissues (n=235) in TCGA, Radvani, Curtis, Ma, Gluck, and Zhao studies." (PMID 26862846, 2016). "CD133 and ly6E have been reported as tumor-initiating cells (TIC) markers for breast cancer and pancreatic Cancer, Nanog and Sox2 are ES cell markers that have been reported in poorly differentiated breast cancer, and correlated with poor survival." (PMID 23705594, 2013). "Furthermore, analysis of the TCGA BRCA breast cancer cohort revealed a significantly higher expression level of LY6E in breast tumor patients compared to healthy individuals, especially in basal subtype of BRCA." (PMID 40634316, 2025). "While most normal tissues have low levels of LY6E expression, common epithelial malignancies, such as breast cancer (64%), pancreatic cancer (63%), non-small-cell lung cancer (56%), and ovarian cancer (53%), commonly have high levels of LY6E expression (IHC 2/3+)." (PMID 39456611, 2024). "LY6E, together with LY6K, has also been implicated in breast cancer proliferation by altering TGFβ-dependent breast cancer cell physiology, resulting in increased immune checkpoint molecules PD-L1 and CTLA4 in tumor-infiltrating T regulatory cells yet decreased natural killer (NK) cell activation." (PMID 31684192, 2019).
breast carcinoma (continued). "High Ly6E mRNA expression in breast cancer was significantly correlated with decreased one-year metastasis free survival (metastasis, n=49 vs metastasis free, n=148), decreased three year metastasis free survival (metastasis, n=168 vs metastasis free, n=426) in Bos, Schmidt, Kao and Hatzis studies." (PMID 26862846, 2016). "High expression of Ly6E was correlated with higher grade of breast cancer." (PMID 26862846, 2016). "LY6A is aberrant expressed in pituitary tumors and can be a tumor-initiating biomarker of lung cancer; LY6E can serve as an independent prognostic factor for CC and is closely associated with the migration and invasion of CC; and LY6K promotes the progression of bladder, ovarian, and breast cancers." (PMID 38067506, 2023). "LY6E promotes signaling via the TGF-β pathway leading to increased drug resistance, PDL1 and CTLA4 expression, and immune escape in breast cancer." (PMID 29545934, 2018).
pancreatic cancer (7 papers, 2011 to 2025). "The LY6E gene has also been associated with more aggressive stem like cells in hepatocellular carcinoma, pancreatic carcinoma, etc.." (PMID 35123499, 2022). "LY6D, LY6E, PSCA, and PLAUR, known markers tumorigenesis and cancer cell maintenance, were significantly associated with lower overall survival outcome in our pancreatic cancer analysis." (PMID 33613843, 2021). "Ly6E mRNA expression was significantly higher in pancreatic cancer (n=10) than precursor (n=5) in Logsdon study." (PMID 26862846, 2016). "Ly6E mRNA expression was significantly increased in pancreatic cancer (n=85) than normal tissues (n=60) in Logsdon, Badea and Pei studies." (PMID 26862846, 2016). "The mRNA expression data across multiple studies shows that ovarian, colorectal, gastric, breast, lung, brain and CNS, cervical, esophageal, head and neck and pancreatic cancers express significant high levels of Ly6D, Ly6E, Ly6H, Ly6K." (PMID 26862846, 2016). "Previous studies demonstrated that LY6D is highly expressed in colorectal cancer and that also LY6E is in pancreatic cancer stem cells." (PMID 21063397, 2011). "Importantly, in pancreatic cancer specifically, LY6E was suggested to be a marker for cancer cells with stem cell properties and was used in addition to the stem cell markers TACSTD1 and CD44 to establish a sorting technique to obtain clonal colony-forming pancreatic cancer stem cells." (PMID 33613843, 2021). "LY6D, LY6E, LY6H, and LY6K have increased mRNA expression in tumor tissues of ovarian, colorectal, gastric, breast, lung, bladder, brain, cervical, esophageal, head and neck, and pancreatic cancer compared to adjacent normal tissues." (PMID 33613843, 2021).
lupus (6 papers, 2010 to 2025). "For example, increased LY6E expression is associated with solid tumorigenesis, angiogenesis, systemic lupus erythematosus, and other abnormalities." (PMID 31739586, 2019). "Indeed, LY6E has been widely associated with inflammation-related abnormalities, including systemic lupus erythematosus (SLE), solid cancer, and viral infections." (PMID 31739586, 2019). "Ly6e, also known as Sca-2 or Thymic Shared Antigen-1 (TSA-1 ), has been identified as a biomarker for systemic lupus erythematosus and shown to be involved in cell-cell adhesion, as well as B-cell and T-cell regulation." (PMID 28446152, 2017). "Because ISG expression reflects serum IFN-I levels, we compared surface CD64 levels on monocytes with the transcript levels of three ISGs (MX1, IFI44, and Ly6E) in PBMCs from lupus patients (n = 108)." (PMID 20478071, 2010).